NAT10 (N-acetyltransferase 10)
Diseases named in the same sentence as NAT10 in open-access papers (continued):
Sharing a sentence is not in itself a finding about the gene and the disease.
prostate carcinoma (continued). "Moreover, the mechanism by which Remodelin inhibits NAT10 in PCa cells involves the regulation of DNA replication to suppress the progression of prostate cancer." (PMID 41316475, 2025). "In addition, targeting NAT10 is considered an effective method for castration‐resistant prostate cancer (CRPC) treatment." (PMID 39817252, 2025). "In prostate cancer (PCa), NAT10 enhances the stability of high mobility group AT-hook 1 (HMGA1) and Keratin 8 (KRT8) by acetylating their mRNAs, hence accelerating cell cycle progression to improve cell proliferation and enhancing EMT progression to facilitate cell migration, respectively." (PMID 41316475, 2025). "In prostate cancer, NAT10 expression has been found to be significantly elevated." (PMID 39764566, 2025). "NAT10 can promote prostate cancer growth and metastasis by catalyzing the formation of ac4C." (PMID 38922788, 2024). "To further analyze the correlation between the protein level of NAT10 and the clinicopathological features of PCa, we stained specimens in the tissue microarray (TMA) of prostate cancer for NAT10 and analyzed them according to the H‐score, as quantitative data of staining intensity." (PMID 38922788, 2024). "However, little is known about NAT10 expression and its role in the acetylation modifications in prostate cancer (PCa)." (PMID 38922788, 2024). "Considering the association of NAT10 expression with AR status and its alterations by AR modulators, there is a possibility that the activity of NAT10 could be involved in the castration treatment of prostate cancers." (PMID 35743017, 2022). "However, the fact that Remodelin still effectively inhibits the growth of castration-resistant prostate cancer cells suggests that targeting NAT10 is a potential strategy for combating CRPC." (PMID 35743017, 2022). "To determine whether the changes in NAT10 in the drug treatment of prostate cancer cells are related to AR, we used AR-negative PC-3 cells and AR-positive VCaP cells for comparison." (PMID 35743017, 2022). "In particular, the relationship between NAT10 and DNA replication suggests that NAT10 may be involved in the regulation of the biological activity of prostate cancer cells." (PMID 35743017, 2022). "NAT10 expression was higher in cancer groups compared with the respective normal groups, including bladder, breast, colorectal, esophageal, gastric, liver, lung, kidney, and prostate cancers, as well as leukemia and myeloma." (PMID 34094911, 2021). "At the same time, to explore the effects of castration on prostate cancer, VCaP cells were subjected to long-term treatment with enzalutamide at either low (2 μM) or high (20 μM) concentrations for at least four weeks, and the expression of NAT10, CDC6, and AR was measured." (PMID 35743017, 2022). "Elevated NAT10 expression significantly promotes cell cycle arrest and EMT in prostate cancer cells, thus advancing malignant progression." (PMID 39764566, 2025). "NAT10 enhances the stability of HMGA1 by acetylating its mRNA, thereby promoting cell cycle progression to improve cell proliferation in prostate cancer." (PMID 40588654, 2025). "Remodelin slowed DNA replication, with NAT10 regulating the expression of CDC6 and MCM7 to promote the growth of prostate cancer cells." (PMID 39764566, 2025). "The results revealed that expression levels of NAT10 and Ki67, CDC6, and MCM7 were increased in prostate cancers." (PMID 35743017, 2022). "The analysis of a TCGA database revealed that the overexpression of NAT10, CDC6, and MCM7 in prostate cancers were correlated with the Gleason score and node metastasis." (PMID 35743017, 2022). "Our data demonstrated that Remodelin, an inhibitor of NAT10, effectively inhibits the growth of prostate cancer cells under either no castration or castration conditions, likely by impairing DNA replication." (PMID 35743017, 2022).
prostate carcinoma (continued). "Although the role of the NAT10 inhibitor Remodelin in various human cancer cells has been explored in recent years, research that is related to prostate cancer is still lacking." (PMID 35743017, 2022). "The expression of NAT10 could be altered under either castration or noncastration conditions, and Remodelin still suppressed the growth of in vitro-induced castration-resistant prostate cancers." (PMID 35743017, 2022).
lung carcinoma (15 papers, 2023 to 2025). "NAT10 dysregulation is linked to various diseases, yet its role in non‐small cell lung cancer (NSCLC) invasion and metastasis remains unclear." (PMID 38826095, 2024). "In lung cancer, studies have shown that NAT10 is upregulated in NSCLC tissues, cell lines, and mouse xenograft models." (PMID 39764566, 2025). "Together, these results confirmed that NAT10 is responsible for RNA ac4C modification in breast and lung cancer cells." (PMID 40138393, 2025). "For example, In lung cancer, studies have shown that NAT10 is upregulated in NSCLC tissues, cell lines, and mouse xenograft models." (PMID 39764566, 2025). "We found that knockdown of NAT10 significantly reduced the expression of LINC02802, and treatment of lung cancer cells with the NAT10 inhibitor remodelin also downregulated LINC02802 expression." (PMID 40860186, 2025). "The NF‐κB signaling pathway is crucial in lung cancer progression, and studies have reported that NAT10 promotes NF‐κB signaling pathway activity in lung cancer, thereby promoting lung cancer progression." (PMID 39764566, 2025). "Here, we found that the expression levels of NAT10-regulated mature miR-9-5p and miR-29-3p were highly expressed in clinical TCGA-Lung cancers compared with normal tissues." (PMID 38308713, 2024). "Knockdown of NAT10 attenuates the oncogenic characters of lung cancer cells by regulating miRNA production in cancers." (PMID 38308713, 2024). "Our data underscore NAT10 as a potential therapeutic target for NSCLC, presenting avenues for targeted intervention against lung cancer through NAT10 inhibition." (PMID 38826095, 2024). "In studies of lung-related diseases, NAT10 is significantly increased in lung cancer tissues and pulmonary epithelia exposed to PM2.5, which was consistent with our results." (PMID 39251905, 2024). "Consistently, the expression levels of pri-miR-9-1/-2 and pri-miR-29b-1 were negatively correlated with NAT10 in clinical TCGA-lung cancers." (PMID 38308713, 2024). "c‐myc upregulates the expression of NAT10, which promotes the proliferation and migration of non‐small cell lung cancer by regulating the cell cycle." (PMID 39640362, 2024). "S4E), suggesting that NAT10 is important for lung cancer brain and extracranial metastases." (PMID 40138393, 2025). "To test whether NAT10 is required for brain metastasis by lung cancer, we used H2030-BrM3 cells, brain metastatic derivatives of the H2030 non–small cell lung cancer cell line harboring the KRASG12C mutation." (PMID 40138393, 2025). "Knockdown of NAT10 induces cell cycle arrest at the G1 phase in lung cancer cells." (PMID 39764566, 2025). "Indeed, the expression levels of pri-miR-9-1 and pri-miR-9-2 were negatively correlated with the expression levels of NAT10 according to analyses of TCGA-Lung cancer RNA-Seq data." (PMID 38308713, 2024). "Furthermore, the expression levels of mature miR-29b-3p in lung cancer tissues were higher than in TCGA normal tissues, and the expression levels of pri-miR-29b-1 was also negatively correlated with NAT10 in TCGA-Lung cancer RNA-Seq data." (PMID 38308713, 2024). "In addition, very similar as miR-9-5p, the relationship of mature miR-29b-3p/pri-miR-29b-1 and NAT10 in lung cancer was obtained." (PMID 38308713, 2024). "However, this study have not been confirmed through in vivo validation, and the expression patterns and functions of NAT10 across different lung cancer subtypes need to be investigated." (PMID 39640362, 2024). "Moreover, the authors reported an important compound that inhibits NAT10 K823‐Khib modification to inhibit lung cancer development, providing a new avenue for antitumor drug development." (PMID 39640362, 2024). "Additionally, we utilized lung cancer patient‐derived 3D organoids, mouse xenograft models, and Remodelin (NAT10 inhibitor) to corroborate these findings." (PMID 38826095, 2024).
lung carcinoma (continued). "Furthermore, we analyzed data from TCGA database to show that the expression levels of mature miR-9-5p in lung cancer tissues (n = 999) were much higher than those in normal tissues (n = 91), indicating that the high levels of NAT10 in cancers up-regulated mature miR-9-5p production." (PMID 38308713, 2024).
multiple myeloma (15 papers, 2021 to 2025). "Together, these findings position NAT10 and its ac4C-associated functions as emerging therapeutic targets in multiple myeloma and other hematological malignancies." (PMID 40973767, 2025). "Likewise, in multiple myeloma, high NAT10 expression levels are associated with a dismal prognosis." (PMID 41316475, 2025). "NAT10 is also upregulated in multiple myeloma (MM), a malignancy characterized by clonal plasma cell expansion in the bone marrow." (PMID 40973767, 2025). "Notably, remodelin, a small-molecule NAT10 inhibitor originally studied in solid tumors, demonstrates anti-myeloma activity in preclinical models." (PMID 40973767, 2025). "In addition, NAT10 promotes the proliferation of multiple myeloma (MM) cells by acetylating CEP170 mRNA, which increases its translation efficiency." (PMID 41316475, 2025). "AcRIP-seq analysis revealed BCL-XL as a downstream target of NAT10 in multiple myeloma." (PMID 40881352, 2025). "On the basis of these findings, researchers have theorized that NAT10 could serve as a potential target and prognostic biomarker for cancer treatment, including multiple myeloma and squamous cell carcinoma of the head and neck (HNSCC)." (PMID 41316475, 2025). "NAT10 improved the translation efficiency of CEP170 by acetylating CEP170 mRNA, which regulating CEP170 during cell mitosis to influence in multiple myeloma progression." (PMID 40588654, 2025). "A recent study has demonstrated that NAT10 enhances the translation efficiency of CEP170 by acetylating its mRNA, thereby promoting the proliferation of multiple myeloma cells." (PMID 38459019, 2024). "Furthermore, given the functional importance of NAT10 in multiple myeloma as well as osteoporosis, targeting NAT10 signaling through selective promoters may be a promising therapeutic strategy for the treatment of osteosarcoma, particularly in patients with high NAT10 levels." (PMID 38233839, 2024). "Similarly, in multiple myeloma, acRIP-seq combined with ribosome profiling sequencing (Ribo-seq) confirmed CEP170 as a critical downstream target of NAT10." (PMID 40881352, 2025). "In multiple myeloma cells, NAT10 acetylates and stabilizes BCL-XL mRNA, which leads to elevated expression of BCL-XL, inhibiting apoptosis and activating the PI3K-AKT pathway, thereby promoting cell cycle progression and proliferation during multiple myeloma malignancy." (PMID 38233839, 2024).
pancreatic cancer (15 papers, 2023 to 2025). "Analysis with single-cell Hub 2 (TISCH2) and the Gene Expression Omnibus (GEO) database for PDAC (GSE154778) showed that NAT10, the only known RNA ac4C writer, was expressed primarily in malignant cells and correlated with increased pancreatic cancer risk." (PMID 40119353, 2025). "Collectively, these results indicate that NAT10 is overexpressed in pancreatic cancer and is associated with a poor prognosis." (PMID 41203621, 2025). "NAT10 is significantly overexpressed in pancreatic cancer tissues and is closely associated with poor prognosis, which is consistent with its oncogenic role in other malignancies, such as cervical and liver cancers." (PMID 41203621, 2025). "Collectively, these results demonstrated that NAT10 promotes pancreatic cancer cell proliferation, migration, and invasion in vitro, highlighting its critical role in malignant progression." (PMID 41203621, 2025). "In conclusion, NAT10 promotes pancreatic cancer progression and immune evasion by regulating the ETS2-PD-L1 axis and stabilizing KRT8 mRNA, highlighting its potential as a therapeutic target for overcoming immunotherapy resistance." (PMID 41203621, 2025). "To gain further insight into the role of NAT10 in pancreatic cancer, we used single-cell sequencing data." (PMID 41203621, 2025). "The body weights of all nude mouse model animals were consistent.These findings underscore the critical role of NAT10 in the promotion of pancreatic cancer growth and metastasis." (PMID 41203621, 2025). "Although the NAT10 signaling pathway reportedly acts as a pro-oncogenic factor in pancreatic cancer, the specific cytosine sites within mRNA regulated by NAT10 in PNI remain unreported." (PMID 40119353, 2025). "Immunohistochemistry (IHC) analysis of samples from 77 patients with pancreatic cancer revealed that the NAT10 protein was predominantly localized in tumor cell nuclei and was significantly elevated in cancerous tissues compared to adjacent normal tissues." (PMID 41203621, 2025). "Single-cell RNA sequencing analysis revealed enhanced interactions between pancreatic cancer epithelial cells with high NAT10 and KRT8 expression, and T cells, thereby providing new insights into the immune microenvironment." (PMID 41203621, 2025). "This study explored the role of NAT10-mediated N4-acetylcytidine (ac4C) RNA modification in pancreatic cancer progression and immune evasion." (PMID 41203621, 2025). "GEPIA confirmed that ETS2 was highly expressed in pancreatic cancer and positively correlated with the expression of NAT10 and PD-L1." (PMID 41203621, 2025). "Single-cell RNA sequencing analysis demonstrated enhanced interactions between pancreatic cancer epithelial cells with high NAT10 and KRT8 expression and T cells." (PMID 41203621, 2025). "Western blotting analysis revealed that ETS2 knockdown reduced the protein levels of both NAT10 and PD-L1 in pancreatic cancer cells." (PMID 41203621, 2025). "NAT10 (N-acetyltransferase 10) is overexpressed in pancreatic cancer tissues and correlates with poor prognosis." (PMID 41203621, 2025). "In this study, we identified NAT10 as a key regulator of pancreatic cancer (PC) progression and immune evasion, primarily through ac4C acetylation-mediated RNA modification." (PMID 41203621, 2025). "Consistent with our findings, recent studies have reported that a novel lncRNA LINC00623 binds to NAT10 and prevents its ubiquitination-dependent degradation, thus influencing mRNA ac4C modification and expression in pancreatic cancer." (PMID 38331765, 2024). "In pancreatic cancer, NAT10 overexpression promotes malignant cell proliferation by activating the PI3K-AKT pathway." (PMID 38233930, 2024). "LINC00623 bound to NAT10 and blocked its ubiquitination-dependent degradation, thereby remodeling ac4C modification of mRNAs in pancreatic cancer." (PMID 38331765, 2024).
pancreatic cancer (continued). "Previous studies have shown that NAT10 promotes proliferation and invasion in malignancies such as gastric, breast, and pancreatic cancers." (PMID 39648231, 2024). "They showed that pancreatic cancer tissues exhibit abnormally increased NAT10 expression, and the patients with the abnormal expression had a poor prognosis." (PMID 38233930, 2024). "Moreover, higher PD-L1 expression was associated with worse prognosis, which was consistent with the disease-free survival (DFS) results of NAT10 in pancreatic cancer." (PMID 41203621, 2025). "Immunohistochemistry (IHC) analysis revealed that NAT10 could inhibit the infiltration of CD8 + T cells in pancreatic cancer tissues, suggesting its immunosuppressive role." (PMID 41203621, 2025). "Furthermore, NAT10 expression was evaluated in pancreatic cancer cell lines (BxPC-3, SW 1990, MIA PaCa-2, AsPC-1, PANC-1, and CFPAC-1) and the normal pancreatic ductal epithelial cell line, hTERT-HPNE." (PMID 41203621, 2025). "Based on these findings, we speculated that NAT10 might regulate PD-L1 to mediate immune evasion in pancreatic cancer." (PMID 41203621, 2025). "We employed single - cell analysis technology to thoroughly examine the binding of NAT10 and KRT8 to T - cell receptors, thereby gaining novel insights into the mechanism underlying NAT10 - regulated KRT8 - mediated immune suppression in pancreatic cancer through ac4C acetylation." (PMID 41203621, 2025). "Additionally, we found that pancreatic cancer epithelial cells with high NAT10 expression have increased interactions with Th1 T cells." (PMID 41203621, 2025). "Indeed, knocking down NAT10 with two siRNAs reduces colony-forming and migration ability of pancreatic cancer cells." (PMID 38233930, 2024). "In pancreatic cancer, NAT10 overexpression has been speculated to confer resistance to gemcitabine." (PMID 41316475, 2025). "Therefore, does NAT10 alter the pancreatic cancer immune microenvironment by affecting Th1 T cells?" (PMID 41203621, 2025). "Thus, abnormal NAT10 expression may promote malignant proliferation of pancreatic cancer by triggering the PI3K-AKT pathway." (PMID 38233930, 2024). "In pancreatic cancer (PDAC), NAT10 acts as an oncogene and promotes tumorigenesis and metastasis both in vivo and in vitro." (PMID 41316475, 2025). "In pancreatic cancer research, lncRNA LINC00623 has been shown to bind NAT10 mRNA and recruit the deubiquitinase USP39, preventing its degradation via the ubiquitin-proteasome pathway and consequently elevating NAT10 expression levels." (PMID 40881352, 2025). "In pancreatic cancer, RNA-seq screening identified the receptor tyrosine kinase AXL as a downstream target of NAT10." (PMID 40881352, 2025). "Our single-cell ligand-receptor bubble plot analysis showed that in pancreatic cancer epithelial cells, the expression levels of MIF, MDK, and LGALS9 were significantly higher when NAT10 and KRT8 were highly expressed than when they were low-expressed." (PMID 41203621, 2025). "The aberrant NAT10 expression also promotes TGF-β signaling and angiogenesis, implying it promotes metastasis of pancreatic cancer cells." (PMID 38233930, 2024). "NAT10 may regulate the expression of adhesion molecules on the surface of tumor cells through KRT8, thereby leading to PD-L1-mediated immune evasion in pancreatic cancer." (PMID 41203621, 2025). "AcRIP-qPCR and mRNA stability assays confirmed that NAT10 boosts AXL mRNA stability in an ac4C-dependent manner, resulting in elevated AXL expression, which in turn promotes the proliferation and metastasis of pancreatic cancer cells." (PMID 40881352, 2025). "Elevated NAT10 expression in pancreatic ductal adenocarcinoma (PDAC) increases the stability and enhances the expression of AXL mRNA through ac4C modification, thereby promoting pancreatic cancer progression." (PMID 39640362, 2024).